ENSG00000212342
Synonyms: LOC124900269
Gene: Small nucleolar RNA gene on chromosome 8 (130,162,972 to 130,163,127, forward strand). Ensembl gene ENSG00000212342.
Gene Ontology:
Biological process: RNA processing
Cellular component: nucleolus
Homologues: Paralogues in human: SNORA12 (82% identical).